TNF (tumor necrosis factor)
Diseases named in the same sentence as TNF in open-access papers (continued):
Sharing a sentence is not in itself a finding about the gene and the disease.
prostate carcinoma (continued). "CX3CR1 in macrophages has been shown to modulate the secretion of proinflammatory cytokines including TNF-α, thus it is likely that the increase in TNF-α release in tumor cells was attributed to the higher level of CX3CR1 in Klf5KR prostate cancer cells." (PMID 38781024, 2024). "It specifically targets NF-κB, leading to the suppression of PMA- and TNF-α-stimulated MMP-9 and VEGF expression in prostatic carcinoma." (PMID 38611849, 2024). "Interruption of Klf5 acetylation, on the one hand, signals iCAFs to release FGF9 via TNF-α; on the other hand, deacetylation of Klf5 induces CX3CR1 expression in prostate cancer cells." (PMID 38781024, 2024). "Cytokines produced during this process, such as interleukin-6 (IL-6), tumor necrosis factor-alpha (TNF-α), and interleukin-8 (IL-8), along with chemokines like CCL2 and CCL12, are thought to be pivotal in bridging the progression to prostate cancer." (PMID 39355131, 2024). "Keywords like microbiota, radiotherapy, gene expression, prostatectomy, IL-6, IL-1β, TNF-α, and STAT3 hold central positions within the prostate cancer domain, reflecting their frequent study." (PMID 39355131, 2024). "In prostate cancer, RCN1 expression increases in the presence of tumor necrosis factor and proinflammatory cytokines in advanced metastasis cancer patients." (PMID 38475805, 2024). "In the immune cell cluster of prostate cancer, formononetin targeted CD74, TNF, HBB, THBS1, INSR, CXCR4, and HSP90AA1." (PMID 38874510, 2024). "Cross-linkage of PSCA-specific UniCAR T cells with prostate cancer cells resulted in a higher IFN-γ and TNF concentration in the supernatants compared to the control." (PMID 36817127, 2023). "In human prostate cancer cells, 6-Shogaol (40 μmol/L) treatment of prostate cancer PC-3, DU145 and LNCaP cells reduced the levels of TNF-α-induced p-NF-kBp65ser536 and the negative regulator p-IKBαS32/36." (PMID 37875983, 2023). "Palbociclib treatment of PSCA-specific UniCAR T cells and CD3-PSCA bsAb-engaged T cells co-cultured with prostate cancer cells resulted in lower total concentrations of IFN-γ and TNF in the supernatants." (PMID 36817127, 2023). "In osteosarcoma and prostate cancer cells, ADCK2 was found to promote the TNFα-mediated accumulation of HIF-1α stability, which, in turn, is associated with the proliferation and survival of cancer cells." (PMID 35205819, 2022). "The ameliorative effect of SeNPs in prostate cancer was indicated by overexpression of necroptosis related to IRF1 and TNF, a decrease in expression of PSA and AR, and an increase in ROS-mediated necroptosis in PC-3 cells." (PMID 36290639, 2022). "Combined progressive AE and RT in prostate cancer patients during and after radiotherapy and androgen deprivation therapy reduced pro-inflammatory cytokine levels and improved QOL, fatigue, and TNF-α levels." (PMID 35935260, 2022). "A functional genomics screen study has shown that TNFα-induced ADCK2 expression in human osteosarcoma cells and prostate cancer cells inhibited ROS production, and it was required for HIF-1α stability." (PMID 36439873, 2022). "For example, prostate cancer-derived exosomes were reported to induce CD73 expression in dendritic cells (DC), which led to an inhibition of tumor necrosis factor-alpha (TNF-α) and IL-12 production by T lymphocytes in an ATP-dependent manner." (PMID 34831276, 2021). "SEVs secreted from prostate cancer cells under hypoxic condition delivered more signaling factors than normal oxygen condition, including TGF‐β, TNF‐α, and IL‐6, thereby promoting cell invasion by altering the tumor microenvironment." (PMID 33508878, 2021). "The bcl-2 gene was transcriptionally regulated by NF-κB and directly links the tumor necrosis factor α, TNF-α/NF-κB signaling pathway with bcl-2 expression and its prosurvival response in human prostate carcinoma cells." (PMID 33815656, 2021).
prostate carcinoma (continued). "Prostate cancer-derived exosomes induced CD73 expression on dendritic cells, which led to an inhibition of tumor necrosis factor-alpha (TNFα) and IL-12 production by T lymphocytes in an ATP-dependent manner." (PMID 31739402, 2019). "The depletion in ADCK2 also significantly decreases the effect of tumor necrosis factor α (TNFα) on hypoxia-inducible factor-1 (HIF-1α) stability in osteosarcoma and prostate cancer cell lines." (PMID 31480808, 2019). "Because TNFAIP8 is a TNFα-inducible protein, we confirmed the expression and identity of TNFAIP8 isoforms by treating three prostate cancer cell lines (PC3, LNCaP, and C4-2) with TNFα and analyzing the induction of TNFAIP8 isoform proteins." (PMID 29928491, 2018). "Vesicular activators of the NF-κB-signaling pathway (e.g., TNF-α and TGF-β) secreted by prostate cancer cells trigger the differentiation of fibroblasts into CAFs, promote stemness, and angiogesis." (PMID 29967610, 2018). "In consequence, we have investigated the effects of TNFα treatment upon the enzymes involved in AEA synthesis and metabolism in human androgen-independent DU145 prostate cancer cells." (PMID 28910408, 2017). "Our data indicates that ADAM19 induces TNF-α shedding in HEK293 cells, and further studies are required to elucidate the effect of TNF-α shedding by ADAM19 and it’s role in human prostate cancer." (PMID 26912236, 2016). "In TRAIL/TNF-resistant prostate cancer cells, pre- or co-treatment to17-AAG with TRAIL/TNF is known to induce high levels of apoptosis through inhibition of the NF-κB or Akt cell survival pathways." (PMID 25883904, 2015). "Another prostate cancer cell line, DU145, which is derived from brain metastasis, was transfected with STAMP1 and STAMP2 and then induced by TNFα." (PMID 25371717, 2014). "In conclusion, the present meta-analysis suggests that the TNF-α-238/A polymorphism is unlikely to be a risk factor for prostate cancer, while the TNF-α-308 G/A polymorphism may make a significant contribution to the risk of prostate cancer in healthy volunteers." (PMID 24666463, 2014). "The effects of the cytokines TNF-α, TRAIL, IFN-γ, IFN-α, IFN-β, IL-13, and IL-1β on cell death and/or cell viability have been investigated in various prostate carcinoma cell lines such as LNCaP, PC-3, DU-145, and M12." (PMID 24982891, 2014). "In DU145 cells, a prostate cancer cell line with moderate invasive potential, only TRIB2 depletion was effective in abrogating TNFα-induced HIF-1α accumulation." (PMID 22355351, 2012). "On the other hand, depletion of PRKAR2B, ADCK2, TRPM7, and TRIB2 significantly decreases the effect of TNFα on HIF-1α stability in osteosarcoma and prostate cancer cell lines." (PMID 22355351, 2012). "A panel of pharmacological inhibitors of MAP kinases produced variable effects on IL-1β- and TNF-α-induced shedding of EPCR in DU-145 and PC-3 prostate cancer cells." (PMID 21320357, 2011). "Further, adhesion of the aggressive prostate cancer cell line PC3 to fibronectin results in upregulation of survivin and protects the cells from apoptosis induced by TNF-α." (PMID 20920299, 2010). "Using DU145 prostate cancer cells, we demonstrate that FGF19 stimulation results in a decrease in TNFα-induced apoptosis." (PMID 21203561, 2010). "One paper, also like ours, demonstrated a positive correlation between CXCR6 levels and Gleason scores, reported CXCL16 expression in prostate cancers, and showed increased secretion of CXCL16 from prostate cell lines after treating with TNF-α." (PMID 19690611, 2009). "In the prostate cancer LNCaP cell line, Humez observed that IGF (5 ng/ml), which increases cell growth, increased ER [Ca2+]ER, whereas TNF alpha (1 ng/ml), which reduces cell proliferation, reduced [Ca2+]ER." (PMID 19554099, 2009).
prostate carcinoma (continued). "Regarding cytokine levels, the prostate cancer nonsupplemented group exhibited a significant posttreatment increase in TNF-α levels (p=0.036), while IL-6 levels remained unchanged." (PMID 40692981, 2025). "We aimed to investigate the effects of a 6-month HOET on interleukin (IL)−1 beta (IL-1ß), IL-2, IL-6, IL-10, IL-12p70, tumor necrosis factor-alpha (TNF-α), interferon-gamma (IFN-γ), and the mGPS of colorectal, breast, and prostate cancer patients after surgery." (PMID 40498221, 2025). "Subsequently, PPI network analysis was conducted on these targets using the STRING database, which suggested that genes such as AKT1, TNF, IL6, STAT3, and CTNNB1 might be key targets for Osthole in the treatment of prostate cancer." (PMID 40978029, 2025). "Furthermore, IFN-γ secreted by natural killer (NK) cells, along with high expression of IFN-γ, TNF-α, IL-5, IL-10, and macrophage inflammatory protein-1 alpha (MIP-1α), has been observed in castration-resistant prostate cancer." (PMID 40430079, 2025). "Prostate cancer-exosomes stimulated the expression of CD73, an ecto-5′-nucleotidase that converts AMP into adenosine, on CD39-positive dendritic cells, leading to ATP-mediated suppression of TNFα and IL-12 secretion." (PMID 40443670, 2025). "Exogenous addition of anti-MTTE together with the LUR1-6 constructs in whole blood also led to increased TNF-α release among memory CD8+ T cells in a prostate cancer patient not previously vaccinated with DTP." (PMID 40520577, 2025). "The enrichment pathways identified following KEGG analysis that contained the most core targets included prostate cancer, the HIF-1 signaling pathway, insulin resistance, the IL-17 signaling pathway, the PI3K-Akt signaling pathway, the TNF signaling pathway, and more." (PMID 38612466, 2024). "Concordant, the GSEA revealed enriched expression of mechanisms and signaling, commonly reported within more aggressive forms of prostate cancer, including EMT, coupled with enriched inflammatory responses, TGF-β receptor signaling and TNFα signaling via NF-kB." (PMID 37031196, 2023). "Consistent with our findings, clinical trial results also suggest that TNF-α levels may specify predictive sensitivity and potency to SMAC mimetics, indicating potential trial investigation for prostate cancer as well." (PMID 37867861, 2023). "Furthermore, Western blot analysis demonstrated that saffron treatment induced changes in the expression of other key genes (DNMT1, DNMT3b, MBD2, CD44, HDAC3, c-Myc, NF-kB, TNFα, AR, N-RAS, and PTEN) in prostate cancer cells." (PMID 38201944, 2023). "Loaded with TNF-α, these polymersomes were found to be four-fold more cytotoxic to the prostate cancer cells than free TNF-α and non-functionalised polymersomes." (PMID 36537575, 2023). "In addition, pioglitazone also plays significant anti-inflammatory roles in the colon and prostate cancer by decreasing COX, TNF, and MCP-1." (PMID 37370809, 2023). "For prostate cancer, missing data for ADT were 1.5% and 16.9% for both IL6 and TNFα." (PMID 36658635, 2023). "BPH tissues and prostate cancer cells express toll-like receptor 4 (TLR4) and are characterized by increased immune-mediated inflammatory processes and secretion of cytokines, such as IL-1β, IL-6, IL-8, TNF-α, and COX-2." (PMID 36771389, 2023). "In prostate cancer, MDK was found to be induced by TNF-α via the NFκB pathway." (PMID 37240085, 2023). "In prostate cancer, ADAM9 cleaves insulin β-chain, tumor necrosis factor (TNF)-α, transforming growth factor (TGF)-α, gelatin, β-casein, etc., and induces the shedding of epidermal growth factor (EGF), fibroblast growth factor receptor 2 (FGFR2)-IIIB and heparin-binding EGF-like growth factor." (PMID 35740916, 2022). "In prostate cancer cell lines HCT116 and LNCaP, TNFα increase PD-L1 mRNA and protein expression." (PMID 33540543, 2021).
prostate carcinoma (continued). "Besides, multiple cancer-related pathways identified were hyperactivated in HIF-1_H, TNF signaling pathway, PI3K-Akt signaling pathway, prostate cancer, and Wallace prostate cancer race." (PMID 32850440, 2020). "Use of a dominant-negative Cx43 that blocks GJIC showed that GJIC sensitizes prostate cancer cells to tumor necrosis factor-alpha (TNFα)-induced apoptosis." (PMID 33321749, 2020). "Prostate cancer cells express chemokine and chemokine receptors, as well as endogenously produced chemokines and cytokines such as MCP-1, TNF-α, IL-1β, IL-6, and IL-8, some of which are secreted at a higher level in PC-3 cells (mCRPC cell line) than in LNCaP cells (mCSPC cell line)." (PMID 33050597, 2020). "While TNFα regulation via miR-130a already has been shown in cervical cancer cells by EGFP reporter assays and Western blotting, only indirect hints on a miR-130a regulation of AR existed so far in prostate carcinoma cell lines and mouse sertoli cells." (PMID 32272867, 2020). "In several prostate cancer cell lines, acetyl-l-carnitine acted as an anti-prostate cancer agent by inhibiting the production of chemokines CXCL12 and CCL2 as well as CXCR4 (chemokine ligand-receptor) and pro-inflammatory cytokines (IFN-γ and TNF-α)." (PMID 32370025, 2020). "We observed that human prostate cancer cells (PC-3, DU145, LNCaP, and LNCaP-SF) express both TNF-α and CCR7 and that low concentrations of TNF-α can induce CCR7 expression in prostate cancer cells through phosphorylation of extracellular signal-regulated kinases in an autocrine manner." (PMID 30871130, 2019). "Antiproliferative efficacy of DAB-Lf dendriplexes encoding TNFα, TRAIL, and IL-12, expressed as IC50 values, in PC-3 and DU145 prostate cancer cells (n.d.: not determined) (n = 15)." (PMID 29493296, 2018). "Furthermore, the KEGG pathway analysis indicated that “prostate cancer”, “TGF-beta signaling pathway”, “TNF signaling pathway”, and “focal adhesion” pathways played an essential role in PCa pathogenesis." (PMID 30027097, 2018). "IL-6, IL-8, and TNF-α, but not IL-1β, are upregulated in prostate carcinoma (CaP) patients with CC compared with those without CC." (PMID 30513776, 2018). "Although there was no significant change in COX-2 mRNA and protein levels, ANXA5 overexpression inhibited COX-2 expression when cells were treated with TNF-α (20 ng/mL), which is known to induce COX-2 mRNA expression in various prostate cancer cells, including PC-3, LNCaP-LN3, and DU145." (PMID 29088783, 2017). "Consistent with the previous studies, we have observed that MSCs pre-stimulated by TNF-α and IFN-γ facilitated the growth of prostate cancer in a syngeneic mouse model, this tumor-promoting effect was accompanied by accumulation of VEGF and PDGF in the mouse serum." (PMID 29268703, 2017). "TNF- α and VEGF both have been reported to contribute to prostate cancer." (PMID 28978058, 2017). "Serum TNF-α, CRP and IL-8 levelswere analyzed in patients with prostate cancer and controls." (PMID 28423553, 2017). "We are aware from our current study, that ADAM19 appears not to be shedding endogenous TNF-α from PC3 prostate cancer cells." (PMID 26912236, 2016). "We found that androgen withdrawal or enzalutamide induced TNF mRNA and protein secretion in castration resistant prostate cancer (C4-2) cells, but not in macrophage-like (THP1) or myofibroblast-like (WPMY1) cells." (PMID 26327448, 2015). "A data driven, multivariate approach, was used in this study to predict prostate cancer cell survival based on the phosphorylation levels of key proteins in PC3, LNCaP, and MDA-PCa-2b cell lines in response to EGF, IGF1, IL6, TNFα, dihydrotestosterone, and docetaxel treatment." (PMID 24885093, 2014).
prostate carcinoma (continued). "Tumor necrosis factor-alpha (TNF-alpha) and TNF-related apoptosis-inducing ligand (TRAIL) are members of the death receptor ligand superfamily and have been suggested as potential anti-prostate cancer agents." (PMID 23743823, 2013). "Similarly, TNF sensitization by lithium in multiple sarcoma cell lines was found to be independent of both GSK-3β and NF-κB while GSK-3β inhibition in prostate cancer and HEK cells actually increased NF-κB activity despite promoting TNF-induced apoptosis." (PMID 22675363, 2012). "Notably, the prostate cancer nonsupplemented subgroup showed a significant posttreatment increase in TNF-α levels (p=0.036)." (PMID 40692981, 2025). "In previous studies, the overexpression of RTN4 in prostate cancer cells was shown to block the cell cycle in the G2/M phase and to induce cell senescence and the expression of inflammatory cytokines, such as CHOP, IL-6, and tumor necrosis factor (TNF)-α, in a muscle cell line (C2C12)." (PMID 36768745, 2023). "Furthermore, TNF-α leads to the induction of CCR7 expression and the CCL21/CCR7 axis may increase the metastatic potential of prostate cancer cells in lymph node metastasis." (PMID 35517503, 2022). "Bone fragments cultured with PC-3 cells showed significantly higher values of OPG and TNF-α expression compared to bone fragments cultured without prostate cancer cells, both in normoxic and hypoxic conditions, while IL-1β expression was significantly higher, only under normoxic condition." (PMID 27765913, 2016). "Consistent with the resistance of CaP cells to clinically relevant doses of TNF-α, this cytokine was shown to increase NFκB signaling and increase expression of c-FLIP, cIAP-1 and Bcl-2, three known NFκB-regulated anti-apoptotic targets in prostate cancer cells." (PMID 26799286, 2016). "However, clinical evidence of an association between TNFα, DHEAS, and DHEA concentrations, and BPH and prostate cancer progression is currently lacking." (PMID 26213785, 2015). "Previous reports have demonstrated a role for SHARPIN in Tumor Necrosis Factor (TNF, also known as TNFα) induced NF-κB activity in MEFs, keratinocytes, B-cells and hepatocytes, as well as in activated B-cell like diffuse large B-cell lymphoma, PC3 and DU145 prostate cancer cells." (PMID 26600301, 2015). "To test our hypothesis that TNF mediates the vascular component of ADT-induced regression, we monitored the effects of castration on the functional and structural properties of the tumor microvasculature in a c-Myc driven, androgen-sensitive prostate cancer model." (PMID 36551505, 2022). "Although previous report demonstrated that TPCK inhibits TRAIL-mediated caspase activity and PDK/AKT signaling in human prostatic carcinoma cell lines, our data indicated that induced AKT signaling by TNFα was not affected by TPCK in myeloma cells." (PMID 24151609, 2013). "For men with prostate cancer, IL6 (b = − 1.423, 95% CI [− 17.894, 15.048], p = 0.866) and TNFα (b = − 1.905, 95% CI [− 8.542, 4.732], p = 0.574) were not statistically significant moderators of the effect of exercise intensity on changes in muscle strength (Model 3.2)." (PMID 36658635, 2023). "However, our screening assay did not identify race-specific differences in serum TNF-α, IFN-γ, and IL-8 levels, whereas IL-6 level was significantly higher in prostate cancer men of AA race than CA." (PMID 37698493, 2023). "Surprisingly, in prostate cancer cell lines, non-bone metastatic DU-145 cells expressed much higher levels of PTX3 expression compared to bone metastatic PC-3 cells, although PTX3 expression was not responsive to TNFα treatment." (PMID 24457902, 2014).
prostate carcinoma (continued). "Testing the prostatic carcinoma cell line PC3 as a further cell system, we could confirm the inhibitory effect of E64d, CA074Me, and zFA-FMK, a further Cath-B inhibitor, on TNF-induced DNA fragmentation (data not shown)." (PMID 14562034, 2003).